PRKD3 (protein kinase D3)
Diseases named in the same sentence as PRKD3 in open-access papers (continued):
Sharing a sentence is not in itself a finding about the gene and the disease.
tumor (16 papers, 2015 to 2026). "Meanwhile, the kinase PRKD3 associated with PCa progression was significantly enriched in subgroup 126, in consistent with the finding that expression of PRKD3 contributes to mast cell infiltration and angiogenesis in the tumor microenvironment of PCa26." (PMID 40180929, 2025). "Collectively, these findings identify PRKD3 as a potential context-dependent modulator of tumor biology, prognosis, and immune interactions, underscoring its potential as a biomarker of diagnostic, prognostic, and therapeutic relevance in precision oncology." (PMID 41931575, 2026). "The positivity of CLU and PRKD3 in TNBC is found to be significantly correlated in clinical TNBC tumor samples." (PMID 33643800, 2021). "Here, protein kinase D3 (PRKD3) is defined to be a key regulator of CLU in promoting TNBC tumor growth." (PMID 33643800, 2021). "In this study, we defined PRKD3 as a key regulator of CLU via inhibiting lysosomal degradation of CLU to promote TNBC tumor growth." (PMID 33643800, 2021). "First, we examined CLU and PRKD3 protein expression level in clinical TNBC tumor samples from patients by immunohistochemical analysis." (PMID 33643800, 2021). "This review discusses the functions and mechanisms of PRKD3 in promoting tumorigenesis and tumor progression of various tumor types as well as the latest developments of small-molecule inhibitors selection for PRKD/PRKD3." (PMID 33403031, 2021). "Consistent with the result of the cell proliferation assay, the volume and weight of the tumour derived from the PRKD3‐knockout cells were significantly smaller and lighter than the ones of the tumour derived from the parental cells." (PMID 31944568, 2020). "Consistent with in vitro cell assays, in mice, tumors formed by PRKD3‐KO TNBC cells show significantly reduced tumor volumes and weights compared to those formed by parental cells, and either ectopic (over)expression of CLU or PRKD3 in PRKD3‐KO TNBC cells can restore TNBC tumor growth." (PMID 33643800, 2021). "Taken together, our data suggest that CLU stabilized by PRKD3 is required for TNBC tumor growth." (PMID 33643800, 2021). "CLU stabilized by PRKD3 is critical for promoting TNBC tumor cell growth in vitro and in vivo." (PMID 33643800, 2021). "Furthermore, the mRNA levels of VEGF, MTA1, PEG10 and hTERT in the PRKD3‐knockout xenograft tumours were lower than that in the parental tumours." (PMID 31944568, 2020). "Additionally, the Western blotting data showed that the amounts of p‐ERK1 (Thr202/Tyr204), p‐c‐MYC (Ser62), c‐MYC in the PRKD3‐knockout xenograft tumours were lower than these in the parental xenograft tumours." (PMID 31944568, 2020). "An analysis of TNBC tumor samples revealed a significant elevation and positive correlation between CLU and PRKD3 protein levels." (PMID 38473804, 2024). "CLU and PRKD3 protein level are significantly elevated and positively correlated in collected TNBC tumor samples." (PMID 33643800, 2021). "Protein kinase D3 (PRKD3) promotes cancer cell proliferation, growth, migration, and invasion in various tumor types." (PMID 34336682, 2021). "CLU silencer (OGX‐011) and PRKDs inhibitor (CRT0066101) can both result in impressive tumor growth suppression in vitro and in vivo, suggesting targeting CLU and its key regulator‐PRKD3 are promisingly efficient against TNBC." (PMID 33643800, 2021). "In TNBC samples, more than 80% (81%) and about 80% (77.2%) TNBC tumor samples are CLU+ and PRKD3+, respectively." (PMID 33643800, 2021). "PRKCD and PRKD3 belong to protein kinase C (PKC) family, whose members also serve as major receptors for phorbol esters, a class of tumor promoters." (PMID 25961669, 2015). "Additionally, the silencing of CLU and PRKD3, through the CLU silencer OGX-011 and the PRKDs inhibitor CRT0066101 suppressed tumor growth both in vitro and in vivo." (PMID 38473804, 2024).
tumor (continued). "In conclusion, we define PRKD3 to be a key regulator of CLU in promoting TNBC tumor growth, and provide new promising targeted therapies against CLU pathway via targeting CLU and PRKD3 as well as serum sCLU as a blood‐based biomarker for efficient management of TNBC." (PMID 33643800, 2021). "In our collected tumor samples from TNBC patients, CLU and PRKD3 protein level are found to be significantly positively correlated, supporting the positive regulatory relation between CLU and PRKD3." (PMID 33643800, 2021). "PRKD3 directly binds and stabilizes CLU to promote TNBC tumor growth." (PMID 33643800, 2021). "The amounts of p‐ERK2 (Thr202/Tyr204) and ERK1/2 were not reduced in the PRKD3‐knockout xenograft tumours." (PMID 31944568, 2020). "We also found that loss of PRKD3 reduced the rate of the cell proliferation in vitro and tumour growth in vivo, whereas ectopic (over)expression of PRKD3, ERK1 or c‐MYC in the PRKD3‐knockout breast cells reverse the suppression of the cell proliferation and tumour growth." (PMID 31944568, 2020).
cancer (12 papers, 2017 to 2026). A tumor composed of atypical neoplastic, often pleomorphic cells that invade other tissues. "These candidate processes and associated genes represent potential mechanisms involved in Prkd3-induced proliferation in spontaneously immortalized cells as well as clinical targets in several cancer types." (PMID 39859313, 2025). "We examined PRKD3 expression, copy number variation, mutation, and DNA methylation, and evaluated their associations with clinicopathological features, patient survival, and diagnostic potential across 33 cancer types." (PMID 41931575, 2026). "Although growing evidence highlights the role of PRKD3 in the tumorigenesis of certain cancers, a comprehensive pan-cancer analysis of PRKD3 remains unavailable." (PMID 41931575, 2026). "The protein kinase D family, including PRKD3, has been demonstrated to play a crucial role in cancer development through its involvement in regulating key cellular processes." (PMID 41931575, 2026). "To address this, we performed an integrative pan-cancer analysis of PRKD3 using multi-omics datasets from The Cancer Genome Atlas, the Genotype-Tissue Expression project, and cBioPortal." (PMID 41931575, 2026). "In multiple cancer types, Protein Kinase D3 (PKD3) has often been reported as a dysregulated oncogenic kinase that promotes cell proliferation." (PMID 39859313, 2025). "Investigation of the transcriptomic changes regulated by Prkd3 in spontaneously immortalized cells is crucial to identify biological markers involved in proliferation that could predict the early risk of cellular transformation associated with cancer development." (PMID 39859313, 2025). "A growing body of data supports that PRKD3 is a promising therapeutic target for the treatment of cancer." (PMID 34336682, 2021). "Last but not least, it would be promising to apply the new emerging proteolysis targeting chimera (PROTAC) for development of new drugs against PRKD3 for cancer treatment." (PMID 33403031, 2021). "In gastric cancer, PRKD3 promotes the development of cancer through RELA proto-oncogene, NF-KB subunit/6-phosphofructo-2-kinase/fructose-2,6-biphosphatase 3 activation of glycolysis." (PMID 33403031, 2021). "The emergence of PRKD3 as a potential therapeutic target for various cancers has encouraged the development of potent, selective, and small-molecule inhibitors." (PMID 33403031, 2021). "The cancer-promoting effect of PRKD3 in HCC had also been studied." (PMID 35281088, 2022). "PRKD3 was reported to play a certain cancer-promoting role in specific types of tumors." (PMID 35281088, 2022). "Accumulating data supports that PRKD3 is a promising therapeutic target for treatment of cancer." (PMID 33403031, 2021). "In this review, we focused on discussing PRKD3 in the context of cancer." (PMID 33403031, 2021). "The integrated phosphoproteomic and transcriptomic analysis in the previous studies showed that PRKD3 may play important roles in a variety of the cancer‐related pathways." (PMID 31944568, 2020). "Therefore, PRKD3‐specific inhibitors should be developed for the cancer patients." (PMID 31944568, 2020). "Due to lack of an autophosphorylation site at its C terminus and the alanine- and proline-rich region at PRKD3 N terminus, PRKD3 exhibits diverse biological effects and molecular signals from other PRKD isoforms in cancer." (PMID 33403031, 2021). "In addition, based on the known functional roles in cancer and the reported classification of the kinase family, PRKD1, PRKD3, BCKDK, PDK2, and CSNK2A2 were considered as potential CCA-relative PKs, which were related to the six overlapped PKs." (PMID 36231050, 2022). "Consistently, when CLU and PRKD3 protein expression level in TNBC sample were quantified and analyzed, both CLU and PRKD3 protein levels are significantly elevated in TNBC cancer tissues compared to paracancerous tissues, and are significantly positively correlated." (PMID 33643800, 2021).
infection (1 paper, 2024). The state of being infected such as from the introduction of a foreign agent such as serum, vaccine, antigenic substance or organism. "We found that both mRNA and protein levels of PKD1(Prkd1), PKD2 (Prkd2), and PKD3 (Prkd3) were increased after HCoV-229E or HCoV-OC43 infection." (PMID 39540754, 2024). "Notably, Prkd3 expression was significantly increased at 6 days post-infection." (PMID 39540754, 2024).
prostate (1 paper, 2025).
PRKD3 also shares sentences with these, for which no sentence is quoted: cardiac hypertrophy (2 papers); hepatocellular carcinoma (2); liver cancer (2); adrenocortical carcinoma (1); familial chylomicronemia syndrome (1); lung adenocarcinoma (1); lung carcinoma (1); Multiple Myeloma (1); stomach cancer (1); thrombosis (1); type 2 diabetes (1).